SLC35C1 (solute carrier family 35 member C1)
Diseases named in the same sentence as SLC35C1 in open-access papers (continued):
Sharing a sentence is not in itself a finding about the gene and the disease.
tumor (6 papers, 2020 to 2025). "Single-cell RNA sequencing analysis further revealed that NOTCH signaling components, such as GALNT11, HES1, KIT, and SLC35C1, are significantly upregulated in tumor-associated monocytes/macrophages." (PMID 40361382, 2025). "In this study, gene co-expression study was further performed to analyze the relationship between SLC35C1 expression and 33 tumor immunity-associated genes." (PMID 37005450, 2023). "In addition, we found that SLC35C1 expression was also closely related to Tumor Mutation Burden (TMB), Microsatellite Instability (MSI) and antitumor drug sensitivity in various cancer types." (PMID 37005450, 2023). "Also, SLC35C1 is associated with various tumor stages, such as HNSC, KIRC, KIRP, LUAD, PAAD." (PMID 37005450, 2023). "We used the Cellminer database to study the correlation between the SLC35C1 gene and anti-tumor drugs, and found that the high expression of the gene SLC35C1 was predicted to be related to resistance to multiple anti-tumor drugs." (PMID 37005450, 2023). "Numerous studies have shown that overexpression of SLC35C1 significantly promotes tumor cell migration and invasion, and that tumor cell migration and invasion can be inhibited by downregulating SLC35C1." (PMID 37005450, 2023). "Because of the small number of normal tissue cases in TCGA database, the normal tissue data from the GTEx database and the tumor tissue data from TCGA database were combined to explored the differences of SLC35C1 expression in 33 cancers." (PMID 37005450, 2023). "More importantly, the expression level of SLC35C1 was closely correlated with Tumor Microenvironment (TME), immune infiltration and immune-related genes." (PMID 37005450, 2023). "This suggests that SLC35C1 is involved in the control of the canonical Wnt/β-catenin pathway, and thereby in tumour cell proliferation and tumour progression." (PMID 33080952, 2020). "Additionally, most analysis studies into the role of SLC35C1 in tumors to date have been limited to a specific kind of tumor." (PMID 37005450, 2023). "The results showed that SLC35C1 could be used as a biological predictor to evaluate drug resistance and drug sensitivity of tumor cells, thus providing new ideas for subsequent clinical research." (PMID 37005450, 2023). "Finally, this study found that SLC35C1 is closely related to tumor immunity, but the study of its specific molecular mechanism is still insufficient." (PMID 37005450, 2023). "In addition, SLC35C1 is significantly correlated with common tumor-related regulatory genes such as TGF BETA SIGNALING, TNFA SIGNALING, pyroptosis, DNA repair, autophagy genes, ferroptosis-related genes, immune checkpoint." (PMID 37005450, 2023). "Finally, we also found that SLC35C1 is also correlated with the expression of many tumor regulatory genes such as TGFβ, SIGNALING, DNA repair, and autophagy genes, and regulates these processes accordingly." (PMID 37005450, 2023). "They demonstrated a reduction in SLC35C1 and an increase in β-catenin at all tumour stages." (PMID 33080952, 2020). "We have been suggested that the reduction of the SLC35C1 level could increase the nuclear translocation of β‐catenin, which activates the signalling cascade and eventually results in the development of tumours." (PMID 31961998, 2020). "Furthermore, SLC35C1 expression has been previously found to be elevated in lung tumors compared to normal tissues in the TCGA cohort, and was also correlated with the tumor microenvironment and tumor molecular burden, microsatellite instability, and antitumor drug sensitivity in cancer." (PMID 39718015, 2024). "Therefore, SLC35C1 may be related to the regulation of tumor immune microenvironment." (PMID 37005450, 2023). "This indicates that abnormal expression of SLC35C1 can affect the response of patients to ICI by affecting the TMB and MSI of tumor." (PMID 37005450, 2023).
cancer (5 papers, 2020 to 2024). A tumor composed of atypical neoplastic, often pleomorphic cells that invade other tissues. "In conclusion, our systematic pan-cancer analysis revealed the biological characteristics of SLC35C1 in cells and tissues and found that SLC35C1 is associated with the risk and prognosis of a variety of tumors." (PMID 37005450, 2023). "Other evidence suggests that SLC35C1 is upexpressed in certain types of cancer and that its high expression is associated with metastasis, poor prognosis and resistance to therapy." (PMID 37005450, 2023). "In this analysis, we comprehensively analyzed the expression levels of SLC35C1 in different kinds of cancers and its relationship with prognosis in several datasets such as TCGA, Genotype Tissue Expression (GTEx), and Cancer Cell Line Encyclopedia (CCLE)." (PMID 37005450, 2023). "Although we performed a comprehensive pan-cancer analysis of SLC35C1, its limitations require further discussion." (PMID 37005450, 2023). "The expression of SLC35C1 is closely related to the PFI of 5 kinds of cancer patients, such as ACC, GBM, KIRC, LGG, and UCEC tumors." (PMID 37005450, 2023). "We estimated the relationship between SLC35C1 expression and the prognosis of cancer patients, with survival indicators including OS and PFI." (PMID 37005450, 2023). "In this study, we performed a comprehensive pan-cancer analysis of SLC35C1 using a series of bioinformatics approaches and validated its differential tissue expression and biological function." (PMID 37005450, 2023). "Second, SLC35C1 was highly expressed in pan-cancer and correlated with clinical outcomes; however, its potential mechanism with rockweed glycosylation in tumors remains to be further investigated." (PMID 37005450, 2023). "The KM-plot results suggest that SLC35C1 is related to the poor PFI of 3 kinds of cancers, including ACC, GBM, LGG." (PMID 37005450, 2023). "The expression of SLC35C1 in 33 cancers in humans was evaluated using TCGA and GTEx datasets." (PMID 37005450, 2023). "GDP-amylose transporter protein 1 (SLC35C1) plays an important role in many types of cancer." (PMID 37005450, 2023). "Thus, multi-omics pan-cancer analysis SLC35C1 not only helps to identify common phenotypic features of tumors, but also provides insight into the genesis of important molecular events and their own regulatory mechanisms." (PMID 37005450, 2023). "In order to deeply study the molecular mechanism of SLC35C1 gene in pan-cancer, we firstly scored all tumors cases with GSVA, and then divided the samples into two groups with high and low expression based on the median of gene expression for comparison between the two groups." (PMID 37005450, 2023). "The study found that SLC35C1 is highly expressed in various human cancer tissues and cells, and its expression level is closely related to the prognosis of patients, which can be regarded as a biomarker of pan-cancer." (PMID 37005450, 2023). "There has been no pan-cancer research of the association between SLC35C1 and various tumors." (PMID 37005450, 2023). "In addition, using publicly available microarray and RNA-seq data, we found that high expressions of FUK, SLC35C1, and FUT8 are generally correlated with poor first progression or relapse-free survival (RFS) in various cancer patient cohorts." (PMID 36961502, 2023).
intestinal diseases (1 paper, 2020). "This study also offers the potential to explore drugs that can restore SLC35C1 to prevent intestinal diseases." (PMID 32655399, 2020).
SLC35C1 also shares sentences with these, for which no sentence is quoted: bacterial infections (1 paper); congenital neutropenia (1); glycogen storage disease type I (1); glycosylation disorders (1); hypoglycaemia (1); microcephaly (1); neutropenia (1); ovarian carcinoma (1); pancreatic cancer (1); Protein-losing enteropathy (1).